ENSG00000292375 (novel transcript)
Gene: Long non-coding RNA gene on chromosome 15 (79,209,403 to 79,230,820, forward strand). Ensembl gene ENSG00000292375.
Gene Ontology:
Biological process: miRNA-mediated post-transcriptional gene silencing
Cellular component: RISC complex